CPSF6 (cleavage and polyadenylation specific factor 6)
Diseases named in the same sentence as CPSF6 in open-access papers (continued):
Sharing a sentence is not in itself a finding about the gene and the disease.
HIV-1 infection (continued). "Having established that CPSF6 promotes HIV-1 infection of MDM, we next aimed to define the replication step affected." (PMID 30672737, 2019). "Some studies suggest that TNPO3 participates in the nuclear import of PICs whereas other authors propose that TNPO3 promotes HIV-1 infection though the interaction with HIV-1 CA or indirectly through the interaction of CPSF6 with HIV-1 CA." (PMID 31465518, 2019). "Since CPSF6 knock-down levels varied between individual cells, we analyzed the correlation between CPSF6 signal intensity and HIV-1 infection at the single-cell level." (PMID 30672737, 2019). "Taken together, these observations suggest that a threshold level of CPSF6 is required for efficient infection of MDM with wild-type HIV-1, and that CPSF6 facilitates HIV-1 infection in a CA-dependent manner." (PMID 30672737, 2019). "We propose that p12 is acting in a similar capacity to CPSF6 in HIV-1 infection by facilitating initial chromatin targeting of CA-containing PICs prior to integration." (PMID 29906285, 2018). "More recent studies indicate that the effect of TNPO3 depletion on HIV-1 infection is mediated by redistribution of the SR protein CPSF6 from the nucleus to the cytoplasm." (PMID 30084827, 2018). "The host factor CPSF6 is known to bind hexameric capsid both in vitro and in cells and influence HIV-1 infection." (PMID 27107820, 2016). "HIV-1 N74D does not bind to the cleavage and polyadenylation specific factor 6 (CPSF6) and is insensitive to an artificially truncated version of this protein (CPSF6-358) which blocks wild-type HIV-1 infection efficiently." (PMID 27279606, 2016). "CPSF6 is primarily nuclear, but manipulation of the C-terminal nuclear localisation signal results in its cytoplasmic accumulation and inhibition of HIV-1 infection [3••,32•,43••]." (PMID 24525292, 2014). "Expression of CPSF6 is required for the HIV-1 infection phenotype observed in human TNPO3-depleted cells." (PMID 25496772, 2014). "One proposed function of CPSF6 during HIV-1 infection is that CPSF6 controls the nuclear entry pathway for HIV-1." (PMID 24415937, 2014). "This work explores the role of cleavage and polyadenylation specificity factor subunit 6 (CPSF6) in the ability of TNPO3-depleted cells to inhibit HIV-1 infection." (PMID 23622145, 2013). "Our findings showed that depletion of TNPO3 expression inhibits HIV-1 infection, while the simultaneous depletion of TNPO3 and CPSF6 expression rescues HIV-1 infection." (PMID 23622145, 2013). "Our siRNA depletion experiments showed that CPSF6 is necessary for the ability of TNPO3-depleted cells to inhibit HIV-1 infection." (PMID 23622145, 2013). "We have demonstrated that inhibition of HIV-1 infection by TNPO3-depleted cells require full-length CPSF6." (PMID 23622145, 2013). "Differently from TNPO3-depleted cells, overexpression of cytosolic full-length CPSF6 inhibited HIV-1 infection before nuclear import." (PMID 23622145, 2013). "Depletion of TNPO3 and CPSF6 completely rescues HIV-1 infection when compared to TNPO3 K.D. HeLa cells transfected with a non-target siRNA." (PMID 23622145, 2013). "The fragment derived from CPSF6 composed of residues 1-358 (CPSF6-358) localizes to the cytoplasm and potently restricts HIV-1 infection when overexpressed in different mammalian cells." (PMID 23622145, 2013). "There is some evidence to suggest that the primary function of TNPO3 during HIV-1 infection is control of CPSF6 localization within the cell." (PMID 24103892, 2013). "The fact that HIV-1-N74D is insensitive to TNPO3-depletion and overcomes the restriction imposed by a fragment derived from CPSF6 suggests a role for CPSF6 in the ability of TNPO3-depleted cells to block HIV-1 infection." (PMID 23622145, 2013). "This work tested the role of CPSF6 in the ability of TNPO3-depleted cells to inhibit HIV-1 infection." (PMID 23622145, 2013).
HIV-1 infection (continued). "Overall, these experiments indicated that CPSF6 is required for the ability of TNPO3-depleted cells to inhibit HIV-1 infection." (PMID 23622145, 2013). "A number of phenotypic similarities suggest the roles of TNPO3, NUP153, NUP358, CPSF6, and CypA during HIV-1 infection are interrelated." (PMID 24103892, 2013). "The importance of the CPSF6 interface in HIV-1 infection is supported by the fact that random drug screening recently resulted in the discovery of a drug, PF-3450074, that inhibits infection and mimics very closely the core F321 residue of CPSF6." (PMID 22956906, 2012). "A C-terminal truncated form of CPSF6 (CPSF6-358) inhibits HIV-1 infection and the TNPO3-independent CA mutant viruses N74D, Q63A/Q67A and E45A are resistant to CPSF6-358 restriction." (PMID 22145813, 2011). "However, the APA changes induced by HIV-1 infection were more modest than those observed after CPSF6 knockdown." (PMID 41405390, 2026). "We observed that both HIV-1 infection and CPSF6-KO reduce CPSF5 expression levels in human cells." (PMID 41405390, 2026). "Because HIV-1 infection mimics the phenotype observed in CPSF6-KO cells, we investigated whether CPSF6 depletion influences SLFN5 expression." (PMID 41405390, 2026). "According to our results, depletion of full-length CPSF6, or expression of a CPSF6 variant lacking only the FG domain, both reduce viral infection compared to cells expressing full-length CPSF6, indicating that the FG domain plays an important role in HIV-1 infection." (PMID 41493399, 2026). "We found that CPSF6 knock-out primary CD4+ T cells are highly permissive to HIV-1 infection." (PMID 41385587, 2025). "Studies of CPSF6 puncta formation in response to HIV-1 infection have reported that cell types differ in initial localization of nuclear CPSF6 prior to infection, with cell types such as HT1080 cells exhibiting diffuse nuclear staining for CPSF6 in uninfected cells." (PMID 41385587, 2025). "To further understand if changing CPSF6’s NLS impacts HIV-1 infection, we utilized single-round HIV-1 luciferase reporter virus to infect our chimeric CPSF6 cell lines, and infectivity was determined as a measurement of viral promoter activity driving reporter gene expression." (PMID 39823525, 2025). "It is unknown if changes to APA can also influence the innate immune response to HIV-1 infection and if this phenomenon is related to the cell-type specific phenotypes observed upon CPSF6 depletion." (PMID 41385587, 2025). "To determine whether the HIV-1 infection phenotype in CPSF6 knock-out cells is strain specific, we repeated our virus challenge experiments with the lab-adapted, CCR5-tropic HIV-1 JR-FL iGFP strain and the CCR5-tropic transmitted founder HIV-1 CH040 strain." (PMID 41385587, 2025). "To study the effects of CPSF6 on PIC function during HIV-1 infection, we quantified DNA replication intermediates (reverse transcription, 2-long terminal repeat [2-LTR] circles for nuclear entry, and integration) in HIV-1-infected cells and evaluated integration site selection profiles." (PMID 40202316, 2025). "The effects of CPSF6 on HIV-1 infection seem to be cell-type dependent." (PMID 40202316, 2025). "However, the C-MYC NLS supported less efficient P90A infection relative to WT HIV-1 infection, while the opposite pattern was observed in cells expressing the CPSF6-HNRNP K chimera." (PMID 39823525, 2025). "Additionally, we observed that cells expressing the CPSF6-NP chimera were more readily infectable with P90A virus, despite inhibiting WT HIV-1 infection." (PMID 39823525, 2025). "It is unknown if APA influences the innate immune response to HIV-1 infection and if this phenomenon is related to the cell-type specific phenotypes observed upon CPSF6 depletion." (PMID 39678349, 2024).
HIV-1 infection (continued). "Collectively, our results demonstrate that the NLS of CPSF6 facilitates steps of HIV-1 infection subsequent to nuclear import and additionally identify the ability of canonical NLS sequences to influence cargo localization in the nucleus following nuclear import." (PMID 38979149, 2024). "Interestingly, we found that some nuclear localized CPSF6-NLS chimeras supported inefficient HIV-1 infection." (PMID 38979149, 2024). "Furthermore, in some cell types, HIV-1 infection has been shown to induce relocalization of nuclear CPSF6 to sites of pre-mRNA processing known as nuclear speckles." (PMID 39678349, 2024). "Conversely, CsA treatment recovered CPSF6 aggregation following WT HIV-1 infection." (PMID 37355754, 2023). "Indeed, in cells depleted of Nup35, POM121, or Nup153, a partial restoration of WT HIV-1 infection is observed after coordinate knockdown of CPSF6, especially in Nup35 and POM121 knockdown cells." (PMID 37355754, 2023). "In addition, the integration pattern of HIV-1 capsid mutant N74D is very similar to the pattern shown by wild-type HIV-1 infection of CPSF6 knockout cells." (PMID 37414787, 2023). "Overall levels of CPSF6 remained consistent before and after HIV-1 infection." (PMID 37355754, 2023). "Remarkably, inhibiting the formation of CPSF6 condensates blocked HIV-1 infection `33 fold." (PMID 37414787, 2023). "We explored the role of CPSF6 condensates in HIV-1 infection." (PMID 37414787, 2023). "These experiments suggested that the formation of CPSF6 condensates is important for wild-type HIV-1 infection but not for viruses bearing the N74D or A77V capsid mutations." (PMID 37414787, 2023). "Additionally, we observed that the integration cofactor LEDGF/p75 changes distribution upon HIV-1 infection and surrounds the CPSF6/CPSF5 condensates." (PMID 37414787, 2023). "The formation of these CPSF6 condensates or puncta-like structures suggested that CPSF6 may be forming biomolecular condensates upon HIV-1 infection." (PMID 37414787, 2023). "The early recruitment of CPSF6 to NS induced by HIV-1 infection requires an intact capsid protein." (PMID 37414787, 2023). "Because CPSF6 forms condensate-like structures in the nucleus upon HIV-1 infection, we determined whether these puncta-like structures were biomolecular condensates." (PMID 37414787, 2023). "To test whether HIV-1 infection of T cells induces the formation of CPSF6/CPSF5 condensates, we challenged Jurkat T cells using HIV-1-GFP at an MOI = 2 for 48 h." (PMID 37414787, 2023). "Our data showed that CPSF6 condensates are important for wild-type HIV-1 infection." (PMID 37414787, 2023). "Remarkably, depletion of CPSF6 did not affect HIV-1 infection, suggesting that the loss of capsid-CPSF6 interactions did not account for the observed decrease in infectivity by the mutants." (PMID 35215956, 2022). "Although the overexpression of full-length CPSF6 remained nuclear and did not block HIV-1 infection, these experiments functionally linked CPSF6 to the HIV-1 capsid." (PMID 35215956, 2022). "Previously reported inhibitory effects on HIV-1 infection upon depletion of the HIV-1 capsid-interacting CPSF6 in cell lines and primary macrophages were ∼threefold, suggesting that the dependency of HIV-1 infection on CPSF6 is particularly high in resting CD4+ T cells." (PMID 34949807, 2022). "TNPO3 depletion led to CPSF6 accumulation in the cytoplasm, which restricted HIV-1 infection." (PMID 34835043, 2021). "Similarly, expression of CPSF6-358 resulted in greater restriction of WT HIV-1 infection than expression of CPSF6-4Glu." (PMID 33758083, 2021). "Higher-order CPSF6 complexes were visualized in the perinuclear region after WT HIV-1 infection but not after N74D HIV-1 infection and were associated with IN-containing complexes and CA (p24) staining." (PMID 33758083, 2021). "They concluded that cytosolic CPSF6 restricts HIV-1 infection before or during nuclear import." (PMID 34064404, 2021).
HIV-1 infection (continued). "However, TNPO3 is also responsible for the nuclear import of CPSF6 which, in HIV-1 infection, favors nuclear transport." (PMID 33868211, 2021). "The integral form of CPSF6, in contrast, favors HIV-1 infection." (PMID 33868211, 2021). "CA plays multiple roles during the early stages of HIV-1 infection, including evasion of cellular innate defenses, mediation of virus nuclear import and, through interaction with CPSF6, transport of VRCs away from the nuclear periphery to sites of vDNA integration (reviewed in Refs." (PMID 32665593, 2020). "In conclusion, we provide a hypothesis that during natural HIV-1 infection, CPSF6 binds to HIV-1 CA, facilitating CA binding to NUP358, thus helps PIC recruitment to NPC." (PMID 32600399, 2020). "This relatively modest effect may be due to the presence of residual CPSF6, since HIV-1 infection preferentially occurred in cells retaining a threshold level of CPSF6." (PMID 30672737, 2019). "Interestingly, this pattern and the observed signal intensities were maintained after CPSF6 knock-down, consistent with our results showing that HIV-1 infection after CPSF6 knock-down preferentially occurs in cells that retain a threshold level of CPSF6." (PMID 30672737, 2019). "Effect of CPSF6 depletion on HIV-1 infection in primary macrophages." (PMID 30672737, 2019). "We observed several CA-dependent, cell cycle-dependent, and cell-type dependent differences in sensitivity to TNPO3 and/or CPSF6 depletion that suggested additional cellular factors may influence their effect on HIV-1 infection." (PMID 30084827, 2018). "Collectively, these data suggest that NUP153 or CPSF6 might have roles in HIV-1 infection beyond their interactions with their binding pocket in CA." (PMID 30084827, 2018). "By tethering the CA-containing PIC to mitotic chromatin, p12 may influence global nuclear targeting of MLV integration, similarly to the proposed role of the CA-binding host protein CPSF6 in HIV-1 infection." (PMID 29906285, 2018). "Furthermore, influencing global nuclear targeting of the PIC by linking capsid to chromatin is reminiscent of the proposed role of the capsid-binding host protein, CPSF6, in HIV-1 infection." (PMID 29906285, 2018). "Further evidence for a link between CPSF6 and TNPO3 include data showing that mutants of TNPO3 that are selectively impaired for interaction with CPSF6 do not support HIV-1 infection, whilst TNPO3-depleted cells are refractory to wild-type HIV-1 infection only in the presence of endogenous CPSF6." (PMID 25356722, 2014). "Here we provide direct evidence for the involvement of endogenous CPSF6 during HIV-1 infection." (PMID 24415937, 2014). "NUP153, CPSF6 and PF74 utilize a distinct sub-set of residues within this site, providing a molecular basis for their associations with capsid and the resulting effects on HIV-1 infection." (PMID 25356722, 2014). "The contribution of CPSF6 to the ability of TNPO3-depleted cells to inhibit HIV-1 infection might be due to a direct effect of CPSF6 on HIV-1 infection." (PMID 23622145, 2013). "Because overexpression of CPSF6-358 blocks HIV-1 infection before nuclear import, CPSF6-358 might be interacting with the incoming viral core." (PMID 23622145, 2013). "While TNPO3 may serve more than one role during HIV-1 infection, altered CPSF6 localization seems to account for a major part of the infectivity defect induced by TNPO3 knockdown." (PMID 24103892, 2013). "For this purpose, we tested the ability of a cytosolic full-length CPSF6 to block HIV-1 infection." (PMID 23622145, 2013). "Because TNPO3-depleted cells inhibit HIV-1 infection in a CPSF6-dependent manner, we tested whether TNPO3-depleted cells inhibit HIV-1 infection by the mechanism used by CPSF6-358." (PMID 23622145, 2013). "How CPSF6-358 would inhibit HIV-1 infection is unclear, but it might inhibit the virus by altering CA stability." (PMID 22145813, 2011).
HIV-1 infection (continued). "Therefore, we next examined whether HIV-1 infection can induce CPSF5 translocation to nuclear speckles in CPSF6-KO cells." (PMID 41405390, 2026). "Finally, we tested whether HIV-1 infection in CPSF6-depleted A549 cells (CPSF6-KO) had an effect on SLFN5 expression, a readout of APA regulation." (PMID 41405390, 2026). "Indeed, we found that in HT1080 cells, which we and others have shown to exhibit relocalization of CPSF6 to nuclear speckles following HIV-1 infection, there is a bias towards 3’ UTR shortening for wild-type infected cells, but not N74D infected cells, at 6 hours post-infection." (PMID 41385587, 2025). "Recent work has shown that CPSF6 puncta represent biomolecular condensates that form via liquid-liquid phase separation, but it is not clear whether CPSF6 needs to accumulate in puncta to facilitate HIV-1 infection." (PMID 38793552, 2024). "Furthermore, HIV-1 infection was sufficient to perturb CPSF6 function and induce changes in APA." (PMID 39678349, 2024). "However, recently, it has been observed that CPSF6 only redistributes to nuclear speckles during WT HIV-1 infection and not during infection with CPSF6-binding deficient mutants A77V and N74D." (PMID 34543344, 2021). "While reduction of CPSF6 expression or loss of capsid binding to CPSF6 in cells does not affect overall HIV-1 infection in most cell types, viral DNA integration is mistargeted outside gene-dense, transcriptionally active host chromatin to heterochromatic lamina-associated domains." (PMID 33758083, 2021). "We have also previously shown that the murine leukaemia virus (MLV) p12 protein binds directly to both CA and nucleosomes, tethering the MLV core to chromatin during mitosis, and have proposed that p12 could be acting in a similar capacity to CPSF6 in HIV-1 infection." (PMID 34543344, 2021). "In contrast, CPSF6 strongly associated with nuclear HIV-1 complexes, and bright nuclear punctae of CPSF6 could be used to identify subviral complexes following HIV-1 infection or lentiviral vector transduction even against the abundant background of CPSF6 in the nucleus." (PMID 30672737, 2019). "Taken together, it is controversial whether CPSF6 has any direct role in HIV-1 infection." (PMID 24415937, 2014). "However, we can hypothesize two scenarios: CPSF6 could become cytoplasmic and restrict HIV-1 infection in specific cell types or after particular stimuli; CPSF6 is a factor required for proper CA core uncoating in certain conditions." (PMID 23414560, 2013). "Irrespective of the role of CPSF6 itself, the conservation and location of the CPSF6 interface, together with the effects of mutations that disrupt it, suggest that it plays an important role in HIV-1 infection." (PMID 22956906, 2012). "In accordance with our data from A549 cells, although of a more limited magnitude, these results show that 3’ UTR shortening events induced by HIV-1 infection of primary CD4+ T cells correlate with the interaction between the viral capsid and CPSF6." (PMID 41405390, 2026). "Upon HIV-1 infection, and simultaneously with these early replication events, the cleavage and polyadenylation specificity factors (CPSF) 5 and CPSF6 are relocalized to nuclear speckles (2, 4, –, 8)." (PMID 41405390, 2026). "In human cells, HIV-1 infection triggers the translocation of CPSF5 and CPSF6 to nuclear speckles; however, the efficiency of this process varies across cell lines." (PMID 41405390, 2026). "These experiments suggest that HIV-1 infection–induced changes in APA depend on the capsid–CPSF6 interaction, and that HIV-1 infection leverages the viral capsid–CPSF6 interaction to modulate the function of the CFIm complex." (PMID 41405390, 2026). "As a control, we quantified the percentage of cells containing CPSF5, CPSF6, and CPSF7 in nuclear speckles upon HIV-1 infection of wild-type and CPSF6-KO cells." (PMID 41405390, 2026).